RRAS2 (RAS related 2)
Diseases named in the same sentence as RRAS2 in open-access papers (continued):
Sharing a sentence is not in itself a finding about the gene and the disease.
breast tumor (2 papers, 2024 to 2025). "Interestingly, a pattern of cancer cell stemness, interactions with the ECM and regulation of the actin cytoskeleton has also emerged from the analysis of the R-RAS2 interactome in a freshly-isolated breast tumor caused by RRAS2 overexpression." (PMID 40221767, 2025). "As for CLL, we could correlate expression of the C allele in homozygosity with a higher expression of the RRAS2 mRNA in the breast tumor samples." (PMID 38987766, 2024). "We also show that sustained RRAS2 expression in murine CBM-MBC21 cells is necessary for metastasis from the primary breast tumor to the lungs and liver." (PMID 40221767, 2025). "Sixty-eight percent of the breast tumors overexpressed RRAS2, with tumors expressing hundreds or even one thousand-fold the levels found in normal tissue." (PMID 38987766, 2024). "The analysis using the Gene Ontology Biological Processes database (GOBP) showed a pattern of mutations in components of the RAS protein signal transduction pathway, which was expected given that the 13 breast tumors emerged in mammary glands overexpressing RRAS2." (PMID 40221767, 2025). "Finally, although we lacked survival data in the AHSB or FIVO cohorts, analysis of the METABRIC data revealed a strong correlation between higher RRAS2 expression in breast tumors and shorter overall survival after diagnosis." (PMID 38987766, 2024). "The grouping of breast tumor samples in the AHSB + FIVO cohorts, according to their pathological classification, showed that RRAS2 overexpression was found in all types of tumors, from in situ to infiltrating carcinomas." (PMID 38987766, 2024). "In regard to their molecular classification, the breast tumor samples with significant RRAS2 gene amplification were Luminal A and Luminal B, but not HER2 + ones." (PMID 38987766, 2024).
cervical cancer (2 papers, 2016 to 2019). A primary or metastatic malignant neoplasm involving the cervix. "The genes encoding VGEF, RRAS2, PRKCB, RASGRP, and PDGFB involved in the six cell-signaling pathways are not currently reported in cervical cancer; however, they were reported as overexpressed in other carcinomas, suggesting their participation in carcinogenesis." (PMID 30696040, 2019).
teratocarcinoma (2 papers, 2017 to 2022). A germ cell tumor characterized by the presence of an embryonal carcinoma component and a teratoma component. "RRAS2, also known as teratocarcinoma oncogene 21 (TC21), being originally cloned from a human teratocarcinoma cDNA library (A. M. Chan, Miki, Meyers, & Aaronson, 1994), shares >50% amino acid sequence homology with HRAS, which reaches 80% when excluding the hypervariable C‐terminal tail." (PMID 36394128, 2022).
triple-negative breast carcinoma (2 papers, 2024 to 2025). An invasive breast carcinoma which is negative for expression of estrogen receptor (ER), progesterone receptor (PR), and human epidermal growth factor receptor 2 (HER2). "However, RRAS2 overexpression is even higher in triple-negative breast cancer and is associated with young age and parity." (PMID 38987766, 2024). "Recent research from our group has shown that the overexpression of the wild-type RAS-family GTPase RRAS2 drives the onset of triple-negative breast cancer (TNBC) in mice following one or more pregnancies." (PMID 40221767, 2025).
Alzheimer disease (1 paper, 2015). A progressive, neurodegenerative disease characterized by loss of function and death of nerve cells in several areas of the brain leading to loss of cognitive function such as memory and language. "For example, we found that SPON1 and RRAS2, overrepresented specifically in L-RG HES5+ cells and thus may relate to gliogenesis, contain SNPs associated with Alzheimer’s disease (P=2.07E−4, Odds=15.26)." (PMID 25799239, 2015).
astrocytomas (1 paper, 2013). "The highest levels of expression were found in grade II astrocytomas (22-fold increase, n = 2), whereas 4-fold increases were detected in grade III astrocytomas (n = 3), confirming that RRAS2 is more strongly overexpressed in lower-grade tumors." (PMID 24148564, 2013). "The only exception was a grade I astrocytoma sample in which low RRAS2 mRNA levels were detected (n = 1), although this may have been due to misclassification." (PMID 24148564, 2013).
cholangiocarcinoma (1 paper, 2024). A carcinoma that arises from the intrahepatic biliary tree (intrahepatic cholangiocarcinoma) or from the junction, or adjacent to the junction, of the right and left hepatic ducts (hilar cholangiocarcinoma). "Additionally, RRAS2-overexpressing mice develop cholangiocarcinomas (unpublished data)." (PMID 38987766, 2024).
colon carcinoma (1 paper, 2022). "In this regard, it has been described that miR-23b inhibits metastasis of colon carcinoma cells by downregulating RRAS2, among other genes, and miR-4448 was identified in a screening of miRNA expression in B cell malignancies versus normal B cells." (PMID 35120522, 2022).
ependymoma (1 paper, 2013). A WHO grade II, slow growing tumor of children and young adults, usually located intraventricularly. "An analysis of RRAS2 expression in a second array of highly malignant CNS tumors, 57 samples from 19 patients, also revealed R-RAS2 overexpression in grade IV medulloblastomas (n = 18), cerebromas (n = 9), meningioma (n = 11), ependymomas (n = 3) and undifferentiated (n = 15) tumors." (PMID 24148564, 2013).
esophageal tumors (1 paper, 2023). "RRAS2 has also been found to be overexpressed in different types of human malignancies: skin cancers, oral cancers or esophageal tumors, although a causal relationship has not yet been established." (PMID 36765602, 2023).
fibrosarcoma (1 paper, 2023). A malignant mesenchymal fibroblastic neoplasm affecting the soft tissue and bone. "This is a specific feature of the mutant RRAS2 alleles, as we obtained similar data when analyzing the mouse fibrosarcoma FS#2 cell line that expresses R-Ras2Q72L endogenously." (PMID 36476833, 2023).
gastric cancer (1 paper, 2021). A primary or metastatic malignant neoplasm involving the stomach. "In addition, we selected the serum of 80 ECs, 80 HCCs, and 80 LCs and measured the titer of four TAAbs (anti-MFGE8, anti-NRAS, anti-PTP4A1, anti-RRAS2) by ELISA to verify the specificity of four TAAbs in gastric cancer." (PMID 33718231, 2021).
germinoma (1 paper, 2016). A malignant germ cell tumor arising in the central nervous system. "Moreover, in our series we identified RRAS-2 as a new player in germinoma pathogenesis, which we found alterated in 14.6% of cases." (PMID 27391150, 2016).
head and neck cancer (1 paper, 2023). A primary or metastatic malignant neoplasm affecting the head and neck. "By contrast, RRAS2 is frequently found overexpressed in a number of human tumors, including B and T cell lymphomas, breast, gastric, head and neck cancers." (PMID 36765602, 2023).
lung diseases (1 paper, 2021). "Further verification was done by qPCR as we tested five differential peak-related genes (Rras2, Ttll12, Ccr3, Ccr6 and Trps1) with known contributions to lung diseases." (PMID 33902609, 2021).
Miscarriage (1 paper, 2024). A pregnancy that ends at a stage in which the fetus is incapable of surviving on its own, defined as the spontaneous loss of a fetus before the 22th week of pregnancy. "RRAS2 expression does not seem to be linked to breastfeeding but is significantly higher in patients who had miscarriages than in those who didn’t, suggesting that rather than with lactation, the highest RRAS2 expression in BC is related to pregnancy." (PMID 38987766, 2024).
neuroblastoma (1 paper, 2017). Neuroblastoma (NB) is the most common solid, extracranial childhood tumor. "However, to our knowledge, recurrent focal amplifications of MYC, ZFHX3, KRAS, RRAS2, and CYTH1 have not been reported in neuroblastoma primary tumors before." (PMID 28924153, 2017).
non-Hodgkin lymphoma (1 paper, 2022). Distinct from Hodgkin lymphoma both morphologically and biologically, non-Hodgkin lymphoma (NHL) is characterized by the absence of Reed-Sternberg cells, can occur at any age, and usually presents as a localized or generalized lymphadenopathy associated with fever and weight loss. "In addition to CLL, RRAS2 mRNA is found overexpressed in other hematological malignancies as well as carcinomas, including non-Hodgkin’s lymphoma, liver hepatocellular carcinoma, and squamous carcinomas of the lung, head, and cervix (PCAWG cohort)." (PMID 35120522, 2022).
papilloma (1 paper, 2015). A benign epithelial neoplasm that projects above the surrounding epithelial surface and consists of villous or arborescent outgrowths of fibrovascular stroma. "The vast majority of chemically induced SCCs in mice have mutations in Hras, Kras or Rras2, and HRasG12V alone is sufficient to induce formation of benign tumors (papillomas)." (PMID 26590320, 2015).
skin tumors (1 paper, 2022). "A common feature of all three tumors on the signal mediation level was the high level of Ras-related protein 2 (RRAS2) expression, which is in line with a study of malignant skin cancer demonstrating increased expression of RRAS2 in highly aggressive skin tumors." (PMID 35055192, 2022).
teratoma (1 paper, 2022). A non-seminomatous germ cell tumor characterized by the presence of various tissues which correspond to the different germinal layers (endoderm, mesoderm, and ectoderm). "In our study, CARD11(caspase recruitment domain family member 11) (mutated in 18% intracranial teratomas), IRS1(insulin receptor substrate 1) (18%), PSMD11(16%), RELN(16%), RRAS2(16%), SMC1A(16%), SYNE1(16%) and ZFHX3(16%) were the tumor-related genes with the highest mutation rates in our cohort." (PMID 36457486, 2022).
cancer (27 papers, 2011 to 2025). A tumor composed of atypical neoplastic, often pleomorphic cells that invade other tissues. "The extensive sequencing of cancer genomes during this last decade revealed that the RRAS2 locus harbors long-tail hotspot mutations (namely, Q72L and Q72H)." (PMID 36476833, 2023). "In contrast to KRAS, the presence of somatic mutations in the coding sequence of RRAS2 is very rare in human cancers." (PMID 38067115, 2023). "Here, we report that many of the RRAS2 mutations found in human cancers are highly transforming when expressed in immortalized cell lines." (PMID 36476833, 2023). "This suggests that, at least for the cell lines tested in this study, the impact of this GTPase on focal adhesion- and invasion-related functions is dependent on the mutational status of the RRAS2 gene in cancer cells." (PMID 36476833, 2023). "Together with our recent work in mice, the present study reinforces the idea that the oncogenic RRAS2 mutations found in tumors are likely important for both cancer initiation and maintenance." (PMID 36476833, 2023). "Although mutations in the coding sequence of RRAS2 have rarely been found in human cancer, we decided to sequence the RRAS2 mRNA in our cohort of 178 patients." (PMID 35120522, 2022). "It is classified into 21 subfamilies, of which only genes in the classic RAS subfamilies (HRAS, NRAS and KRAS) and RRAS2 have been seen to carry mutations in human cancers." (PMID 24148564, 2013). "RRAS2 is a RAS-related GTPase rarely found mutated in cancer." (PMID 38987766, 2024). "Using this server, we found that a missense mutation in RRAS2 (Gln72 to Leu) might serve as an allosteric driver of tumorigenesis, revealing the mechanism of the mutation in knock-in mice and cancer patients." (PMID 37078611, 2023). "For example, RRAS2, which encode a Ras-related GTPase with transforming potential similar to H-, K- and N-Ras, is a well-known oncogene and has been implicated in the pathogenesis of human cancer." (PMID 21789222, 2011). "RRAS2 is crucial in cancer cells with constitutively active classical RAS proteins, indicating these GTPases are not functionally redundant." (PMID 39788953, 2025). "The functional dysregulation of RRAS2 has been shown to contribute to oncogenesis, as it triggers critical biological processes in cancer cells, including proliferation, migration, the epithelial–mesenchymal transition, and resistance to chemotherapy." (PMID 36827160, 2023). "Abnormal activation of Ras proteins (including RRAS2, MRas, HRas, KRas, and NRas) is the primary stimulus of oncogenes that has an essential role in the main signaling pathway in cancer." (PMID 36251702, 2022). "In contrast, gene alterations affecting the RRAS2 locus have been found in less than 1% of all cancers and those alterations involve mostly gene amplifications." (PMID 35120522, 2022). "Among cancer-related genes, CARD11(18%) and IRS1(18%) were the most common somatic mutated genes, followed by PSMD11, RELN, RRAS2, SMC1A, SYNE1 and ZFHX3, and the mutation rates of the latter six genes were all 14%." (PMID 36457486, 2022). "However, much other research also reported that RRAS2 was overexpressed in various cancers, indicating its carcinogenic potential." (PMID 41023110, 2025). "Three of these genes (RELN, IRS2, and FOXP1) have a known association with non-CRC digestive cancers and one (RRAS2) has a known association with non-CRC cancer." (PMID 37627102, 2023). "LPS treatment induced cancer-related genes in the liver, including Kras, Rras2, and Raf1." (PMID 37505851, 2023). "Against the current view that RAS family members cause cancer after acquiring activating mutations, we show here that RRAS2 does not require activating “oncogenic” mutations in its coding sequence to induce cancer." (PMID 35120522, 2022). "In spite of frequently finding RRAS2 mRNA and/or protein overexpressed in human cancers, a causal relationship has not been clearly established." (PMID 35120522, 2022).
cancer (continued). "Additionally, direct R-RAS2 inhibitors could provide a targeted treatment approach for cancers overexpressing RRAS2, including TNBC, CLL, and potentially other malignancies." (PMID 40221767, 2025). "Unlike classical RAS genes, oncogenic mutations on RRAS2 are seldomly found in human cancer." (PMID 36765602, 2023). "In support for the relevance of overexpression of wild type RRAS2 in human cancer, we have found that RRAS2 expression is influenced by the presence of a specific single nucleotide polymorphism (SNP) located in the 3’-untranslated region (UTR) of the RRAS2 mRNA." (PMID 36765602, 2023). "Unlike for KRAS, oncogenic mutations in RRAS2 are rarely found in human cancer." (PMID 35120522, 2022). "Hence, there is strong evidence that RRAS2 may be involved in the transformation related to different types of cancer." (PMID 24148564, 2013). "The abnormal function of RRAS2 is a triggering factor that perturbs downstream tumor signaling cascades (such as MEK-ERK signaling and the PI3K-mTOR pathway), promoting malignant transitions in various cancers." (PMID 37078611, 2023). "Recent research from our group has demonstrated that, contrary to what is the usual cancer development process through missense mutations, B-CLL is driven by the overexpression of the small GTPase RRAS2 in its wild-type form without activating mutations." (PMID 38136362, 2023). "Unlike some other cancers linked to the KRAS gene, CLL is associated with a gene called RRAS2, which is overly active but not mutated." (PMID 38136362, 2023). "Notably, the specific HCGs shared by both cancer cell lines included CDKN2A, CDKN2B, and MTAP deletions on chromosome 9 and RRAS2 insertions on chromosome 11." (PMID 35570408, 2022). "Thus, promoting the anti-aging mechanism of RRAS2 without leading to cancers is a research direction worth exploring as well." (PMID 41023110, 2025).
tumor (16 papers, 2013 to 2025). "Such increased distance to the origin points out to a higher than normal abundance of genomic DNA encoding the RRAS2 gene in both tumor and blood from BC patients." (PMID 38987766, 2024). "Although activating mutations in RRAS2 are seldom found in human BC (they are found in 3 of 8,906 tumor samples; cBioportal.org), the somatic mutation G23S in the endogenous Rras2 locus suggests another step in BC evolution on top of wild-type RRAS2 overexpression." (PMID 40221767, 2025). "To explore these interactions, we generated a cell line from a primary TNBC tumor in RRAS2-overexpressing mice and established a knockdown cell line with a fourfold reduction in R-RAS2 protein levels." (PMID 40221767, 2025). "Experimental studies have confirmed the overexpression of Ras-related protein RRAS2 in cSCC, and the interference of RRAS2 expression impairs angiogenesis, colony formation, and tumor sphere formation." (PMID 39925808, 2025). "On the other side, tumor formation provoked by RRAS2 overexpression is accompanied by increased mammary gland epithelial cell proliferation (NES = + 2.1) and by an increase in extracellular matrix (collagen) biosynthesis and modifying enzymes (NES = + 1.8)." (PMID 38987766, 2024). "The result showed that the TNBC tumor type developed in RRAS2-overexpressing mice resemble more the mesenchymal stem-like (MSL) subtype than any of the other." (PMID 38987766, 2024). "The Rras2 G23S mutations were all found in tumors from parous female mice that were not either pregnant or lactating at the time of tumor finding." (PMID 40221767, 2025). "Additionally, RRAS2 showed a significantly higher expression in tumor samples obtained from patients relapsing after therapy compared to those obtained before therapy." (PMID 38987766, 2024). "When we assessed RRAS1, RRAS2 and RRAS3 expression according to tumor type and grade, the expression of RRAS1 and RRAS2, but not that of RRAS3, was significantly stronger in grade I and II tumors than in grade III tumors (p < 0.01)." (PMID 24148564, 2013). "Here, we need to point out that we have analyzed genomic DNA from total blood and therefore the results of RRAS2 gene abundance derive from total non-transformed blood cells and not from a minority of circulating tumor cells." (PMID 38987766, 2024). "Although no RIT1, RRAS2, or MRAS mutations were found in the TCGA BC dataset, one tumor with undetermined ER and HER2 statuses harbored a RAC1 (P69S) mutation, and one TNBC tumor harbored a RHOB (D13Y) mutation." (PMID 28636652, 2017). "The analysis of RRAS2 expression in non-tumoral mammary gland tissue of Rosa26-RRAS2fl/fl x Sox2-Cre mice shows a mean 3.2-fold above the expression of the murine Rras2 gene in non-tumor developing control breeders." (PMID 38987766, 2024).
CNS tumors (1 paper, 2013). "RRAS2 overexpression in human CNS tumors was confirmed by RT-qPCR in tissue samples from 32 patients." (PMID 24148564, 2013). "RRAS2 gene expression was compared by qPCR with that of the other 2 genes in this R-RAS subfamily (RRAS1 and RRAS3) in the same CNS tumor samples (n = 32)." (PMID 24148564, 2013).
metabolic disorders (1 paper, 2023). "In addition to these genes, variants were found in seven genes (ALDOB, MASP1, KIAA1109, TRAPPC4, SMARCAL1, HERC1, RRAS2) that were previously not reported in MPS but associated with other metabolic disorders." (PMID 37091798, 2023).
RRAS2 also shares sentences with these, for which no sentence is quoted: infection (6 papers); B cell lymphomas (2); CNS cancers (2); colorectal cancer (2); hepatocellular carcinoma (2); T-cell acute lymphoblastic leukemia (2); viral infection (2); acute lymphoblastic leukemia (1); benign tumors (1); Brugada syndrome (1); congenital generalized lipodystrophy (1); esophagus cancer (1); Frasier syndrome (1); glioblastoma (1); glioma (1); Kallmann syndrome (1); lysosomal storage disorders (1); medulloblastoma (1); meningioma (1); myopathy (1); oligodendroglioma (1); oral cancers (1); osteosarcoma (1); Renal cyst (1); Splenomegaly (1); squamous carcinomas (1); T cell lymphomas (1); type A thymomas (1); uveal melanoma (1).